LEP (leptin)
Diseases named in the same sentence as LEP in open-access papers (continued):
Sharing a sentence is not in itself a finding about the gene and the disease.
Obesity (continued). "Leptin, which has a fundamental role in the pathogenesis of obesity, also affects a broad spectrum of depressive disorders by the regulation of the HPA axis, and by promoting the activity of BDNF." (PMID 39000142, 2024). "This agonist was further validated as a leptin surrogate in in vitro cell functions, demonstrating its potential for the treatment of obesity and diabetes." (PMID 38672473, 2024). "Leptin levels are significantly higher in individuals with obesity compared to those with normal weight, and a substantial correlation exists between leptin levels and BMI." (PMID 38562155, 2024). "It was suggested that excess leptin plays a major role in increased BP among individuals with obesity." (PMID 37872379, 2024). "While bariatric surgery is effective for common obesity, its success relies on a functional leptin-melanocortin pathway." (PMID 39777073, 2024). "Based on investigations of leptin and its receptor, an association was observed between PTC and DTC with obesity." (PMID 38392069, 2024). "Although several hundred adipokines have been discovered so far, in relation to obesity, attention is most often focused on the adipokines, resistin, visfatin, and leptin." (PMID 39795949, 2024). "Given the anticipated growth rates of obesity in the coming decades, further research into the functions and mechanisms of specific adipokines, such as leptin, is crucial." (PMID 38397015, 2024). "The ADPN:LEP ratio is a prognostic factor for the development of obesity, cardiovascular disease, insulin resistance, and diabetes, as well as several other conditions, due to the ubiquity of LEP and ADPN in the human body." (PMID 39194505, 2024). "For example, p.N103K was identified in a subject with obesity and very low serum leptin, yet expression and secretion were comparable to WT leptin in our studies." (PMID 39002670, 2024). "Our study demonstrated that prolonged HFD exposure in mice resulted in significant metabolic dysfunctions, including obesity, impaired glucose metabolism, elevated leptin levels, and decreased ghrelin levels." (PMID 39724960, 2024). "The evidence indicates that central leptin resistance is a key factor in the development of obesity." (PMID 38397015, 2024). "Many LEPR variants are currently under investigation for their possible link to leptin resistance and obesity, the most important are rs1137100 and rs1137101." (PMID 39203789, 2024). "Obesity leads to chronic leptin elevation, produced by epicardial adipose tissue or by dysfunctional subcutaneous or visceral adipose tissue." (PMID 39682585, 2024). "Clinical conditions that typically elevate prolactin or leptin levels, such as pregnancy, obesity, or treatment with antipsychotic drugs, have also been associated with an increased risk of thromboembolic events." (PMID 38255892, 2024). "In obesity, an alteration of the normal production of adipokines, especially leptin and adiponectin, is also observed." (PMID 39410050, 2024). "The common denominator in MO and SO diseases is that most of these patients have a defect in the leptin-melanocortin pathway that leads to early-onset obesity and hyperphagia (defined by impaired satiety and satiation leading to food-seeking behaviour)." (PMID 39050109, 2024). "This illustrates the fact that the complex relationships between adiposity, plasma leptin, plasma adiponectin, and insulin resistance lie beyond obesity." (PMID 38289144, 2024). "Obesity and T2D are distinguished by high and low serum levels of leptin and adiponectin, respectively." (PMID 38991370, 2024). "In contrast to leptin, adiponectin tends to be decreased in obesity, and, since one of its main actions is to regulate glucose metabolism, decreased adiponectin tends to promote a diabetic effect." (PMID 39593945, 2024).
Obesity (continued). "Leptin is already licenced for use as a drug to treat obesity, and, in clinical studies, treatment with leptin is very effective as it dramatically reduces body weight in individuals with morbid obesity attributed to recessive ob gene mutations." (PMID 39000459, 2024). "This meta-analysis analyzed leptin in individuals with diabetes or obesity and emphasized the importance of monitoring serum/plasma leptin levels in patients with these diseases." (PMID 39684379, 2024). "Of these, leptin is secreted by adipocytes and is particularly elevated in obesity and hypertension." (PMID 39217385, 2024). "Another mechanism involved in the occurrence of hypertension and obesity is leptin and the leptin–melanocortin pathway." (PMID 39457606, 2024). "In these human studies, it seems that the relationship between leptin and prolactin is mediated by obesity, and the relationship between leptin and milk volume is mediated by prolactin." (PMID 39770967, 2024). "In a recent study on obesity, significant improvements in weight and glucose tolerance were observed in obese rats following the administration of a monoclonal leptin antibody." (PMID 38263019, 2024). "An important molecular link between obesity and antitumor resistance is increased leptin secretion, which can affect the intrinsic molecular characteristics of breast cancer cells and influence the therapeutic response of patients." (PMID 38228661, 2024). "Obesity primarily contributes to chronic low-grade inflammation by releasing a surge of signaling molecules, including the adipokines leptin and resistin, the cytokine interleukin-6 (IL-6), and the chemokine monocyte chemoattractant protein-1 (MCP-1)." (PMID 39717478, 2024). "In early obesity, leptin signalling regulates NLRP3 inflammasome activation that supports M1 macrophage infiltration." (PMID 38580672, 2024). "The mean concentration of Leptin in the group with normal body weight was 102 ng/mL; in the overweight group, it was 175.7 ng/mL; and in the group with obesity, the mean concentration was 296.95 ng/mL." (PMID 38786737, 2024). "Obesity leads to insulin resistance and an imbalance in circulating adipokines, characterized by increased levels of leptin and decreased levels of adiponectin." (PMID 39767708, 2024). "Our study, a placebo-controlled randomized trial, delves into the efficacy of specific dietary fiber supplements—glucomannan, inulin, and psyllium—in individuals with obesity-related genetic polymorphisms within genes such as FTO, LEP, LEPR, and MC4R." (PMID 38398881, 2024). "Obesity is widely regarded as a pro-inflammatory state, and leptin, an appetite-regulatory hormone produced by white adipose tissue, is being studied as a link between obesity and inflammation." (PMID 38279728, 2024). "Studies show that obesity can cause changes in baseline levels of insulin, insulin-like growth factor-1 (IGF-1), leptin, adiponectin, steroid hormones, and some cytokines." (PMID 39042663, 2024). "Increases in leptin concentrations were particularly observed in adolescents living with pre-pregnancy overweight or obesity." (PMID 38999894, 2024). "In this context, increased leptin level, a common finding in obesity, is strongly associated with insulin resistance partially through increased adiposity, which suggests an overall decrease in sensitivity to leptin and insulin in obesity." (PMID 38289144, 2024). "Another study showed that hypermethylation of the POMC promoter gene and hypomethylation of the NPY promoter gene interferes with the binding of transcription factors, and blocks the effect of high leptin levels, thus leading to obesity." (PMID 38707092, 2024). "This study is the first study in Turkey addressing the positive effects of breastfeeding on obesity and it aims to explain the epigenetic mechanisms of the relationship between breast milk and the leptin gene." (PMID 39594868, 2024).
Obesity (continued). "With high statistical significance, proteins FABP4, FCN2, and LEP showed 2-fold, 2.6-fold, and 4-fold increases in expression in the group of individuals with obesity, respectively." (PMID 38732002, 2024). "This study provides invaluable insights into the complex world of leptin resistance and its modulation, thereby contributing to endocrinology, metabolism, and obesity." (PMID 39916981, 2024). "The ability to demonstrate hypertrophy in mice with inactivated ObR despite reduced ObR-dependent signalling suggested other underlying mechanisms of hypertrophy unrelated to leptin or STAT3, at least in these obesity models." (PMID 38256208, 2024). "Patients with mutations in the leptin-melanocortin pathway and BBS often receive dietary and exercise counseling similar to those with polygenic obesity, yet they show limited response to these lifestyle changes, as seen in MC4R deficiency." (PMID 39777073, 2024). "Denisova E.I., Savinkova M.M., Makarova E.N. Influence of leptin administrationto pregnant female mice on obesity development, tastepreferences, and gene expression in the liver and muscles of their male and female offspring." (PMID 38952707, 2024). "The alternative explanation is that a fat-derived hormone, leptin, plays a role between obesity and testosterone." (PMID 38915014, 2024). "It has been found that SCFAs can promote leptin secretion in adipocytes by activating FFARs, thereby regulating appetite and improving obesity." (PMID 39000282, 2024). "Both leptin resistance in obesity and disrupted leptin signaling in Alzheimer’s disease share a common pathway of cognitive impairment, particularly affecting memory and executive function both in rodents and humans." (PMID 39594988, 2024). "Some studies have demonstrated the role of leptin as a respiratory stimulant, and how leptin resistance related to obesity can contribute to a decline in respiratory control." (PMID 38966619, 2024). "Furthermore, bioactive factors such as appetite-regulating hormones, e.g., ghrelin, adiponectin, and leptin, that are present in breastmilk may contribute to appetite regulation and prevent excess energy intake, in turn reducing risk of obesity in the long term." (PMID 37977327, 2024). "In boys (280 with normal weight, 118 with overweight, and 105 with obesity), from normal weight to obesity, plasma leptin and LAR also increased significantly (p < 0.001), while differences in plasma adiponectin were not significant (p = 0.368)." (PMID 38289144, 2024). "Although body condition scoring is less precise than direct weighing and serum leptin measurements for assessing obesity, we hope our study draws attention to the welfare concerns, including obesity, of captive Asian elephants in China." (PMID 39765475, 2024). "Meanwhile, the generation of adiponectin, leptin, visfatin, retinol binding protein-4 and resistin become irregularly and the production of free fatty acids begins to increase, then the obesity-related syndromes occurred and worsen." (PMID 38475734, 2024). "Dysfunctional adipocytes in obesity release an unbalanced mixture of adipokines (like insulin and leptin), metabolites (like cholesterol and free fatty acids), and cytokines (like TNFα and interleukins)." (PMID 39040042, 2024). "Pregnant women with obesity and PE exhibit higher leptin levels, correlating with increased Tumor Necrosis Factor-Alfa (TNF-α), Interleukin 6 (IL-6), and C-reactive protein concentrations." (PMID 38750456, 2024). "Experimental models have shed light on the connections between AD and obesity, implicating adipokines like leptin and adiponectin in both conditions." (PMID 38673730, 2024). "In one study, ablation of very long chain FA elongase 3 in mice attenuated their serum leptin and triglyceride levels and lipogenic gene expression in the liver, making them completely resistant to diet-induced obesity." (PMID 38980850, 2024).
Obesity (continued). "Obesity is recognized as a factor that can worsen AR symptoms, and simultaneously, it correlates with heightened levels of IL-1β and leptin." (PMID 38790590, 2024). "Obesity is considered to promote PI3K/Akt signaling through mechanisms involving increased levels of insulin and leptin, and possible relationships between obesity, IGFBP7 expression, and ganitumab sensitivity deserve further study." (PMID 39362991, 2024). "Nevertheless, there is evidence from rodent and human studies that high levels of leptin accompanied by a low leptin response are detected in obesity." (PMID 39229323, 2024). "can prevent metabolic disorders and obesity by reducing serum leptin levels and fasting blood glucose concentration and improving glucose tolerance." (PMID 39272484, 2024). "Hippocampal leptin resistance has relevant clinical implications for cognitive decline, particularly within the context of obesity and metabolic disorders." (PMID 39594988, 2024). "Among the mechanisms that promote the development of obesity is circadian dysregulation, which affects metabolism and the release of appetite-related hormones, such as leptin and ghrelin." (PMID 39598301, 2024). "Obesity increases leptin secretion, leading to an excess of cholesterol secreted into the bile, which raises the risk of gallstones." (PMID 38840060, 2024). "Historically, there was an assumption that leptin therapy would have a similar potential effect on the treatment of common obesity, also referred to as diet-induced obesity." (PMID 38707092, 2024). "Adipose tissue, which is a characteristic of obesity, is known to foster chronic inflammation, potentially inducing an overproduction of leptin." (PMID 38887300, 2024). "Perhaps the most likely explanation for the limited progress toward understanding leptin biology in human obesity is the unavailability of leptin for human clinical investigations." (PMID 38165042, 2024). "Individuals with obesity often exhibit high leptin concentrations and adipokines with pro-inflammatory properties." (PMID 39457561, 2024). "Individuals with obesity have a phenomenon known as central leptin resistance, resulting in elevated levels of leptin." (PMID 38255708, 2024). "Psoriasis and obesity share some cytokines with proinflammatory activity, like TNF-α, IL-1, and IL-6 and some adipokines (i.e., adiponectin, leptin, resistin, or lipocalin) with a pathogenic role in both diseases." (PMID 39062334, 2024). "The growing body of evidence suggests that the relationship between circadian disruption and obesity is driven by alterations in the hormonal rhythmicity of melatonin, leptin, and glucocorticoids, leading to disruptions in energy homeostasis." (PMID 38838328, 2024). "Other studies reported a positive correlation between resistin and leptin serum levels in metabolic syndrome, obesity, and diabetes mellitus type 2." (PMID 39062875, 2024). "Taken together, these findings provide strong evidence that IPA counteracts obesity by enhancing leptin sensitivity." (PMID 39606796, 2024). "Peripheral estrogen exerts autocrine and paracrine effects that contribute to increased body mass, alongside elevated BDNF and leptin levels, in the context of central BDNF deficiency— an occurrence referred to as "obesity protecting obesity"." (PMID 39655343, 2024). "The dysregulation of leptin in obesity not only affects the secretion of gonadotropin-releasing hormone (GnRH) but also influences fertility hormone production, potentially leading to infertility." (PMID 38398459, 2024). "Leptin, a cytokine secreted by fat cells that regulates energy balance, is abnormally elevated relative to the degree of obesity in patients with CP." (PMID 38965454, 2024). "In the presence of obesity, the level of this adipokine is elevated (hyperleptinemia) but does not fulfill the role of reducing food intake or body mass index, indicating leptin resistance." (PMID 39683415, 2024).
Obesity (continued). "Pathways related to growth and nutrient utilization (Regulation of eIF4 and p70S6K Signaling, Insulin Secretion Signaling, PPAR Signaling, Leptin Signaling in Obesity) were all inhibited, suggesting cardiac metabolic dysregulation." (PMID 38981849, 2024). "Leptin surrogates, which have much longer half-life in the body, have potential in the treatment of obesity and diabetes." (PMID 38672473, 2024). "Paradoxical to plasma leptin levels, midlife obesity results in lowered plasma adiponectin levels, while late-life weight loss results in elevated adiponectin levels." (PMID 38892118, 2024). "Women with obesity have elevated pro-inflammatory chemokines, leptin, and insulin HM content compared to peers with normal weight." (PMID 38544749, 2024). "Rather, metreleptin plays a limited role in the treatment of common obesity due to the presence of high leptin levels in the circulation of these patients." (PMID 38707092, 2024). "Each of these mechanisms underscores the complex interplay between metabolic dysfunction and leptin signaling, highlighting the challenges in managing leptin resistance and obesity." (PMID 39916981, 2024). "The epigenetic markers involved in leptin resistance serve as therapeutic targets for obesity and its related comorbidities." (PMID 38707092, 2024). "Recent clinical trials have explored various amylin analogs, including pramlintide, cagrilintide, davalintide (AC2307) and GUBamy (GUB014295), that have demonstrated potential in addressing overweight and/or obesity due to their actions as leptin sensitizers." (PMID 39594988, 2024). "It is worthy to note that leptin’s tendency for resistance and the multiple mechanisms involved made it a less ideal target in developing effective leptin analogs for treating obesity." (PMID 39145170, 2024). "Leptin is a hormone capable of effectively reducing food intake and body weight, initially suggesting its potential in obesity treatment." (PMID 38397015, 2024). "As one of the most common side effects of insulin treatment remains significant weight gain, combining it with leptin-neutralizing antibodies would restore leptin sensitivity and prove beneficial for the management of obesity in type 2 DM." (PMID 38707092, 2024). "Secondly, increased leptin levels in obesity can influence the hypothalamus-pituitary-thyroid (HPT) axis and consequently the endocrine system." (PMID 38498431, 2024). "Leptin has pleiotropic effects on the physiology and pathophysiology of energy homeostasis, endocrine glands, and metabolism, and numerous studies have found a positive correlation between leptin levels and obesity and the development of metabolic syndrome." (PMID 39143842, 2024). "In order to evaluate the dyslipidaemia associated with obesity, HDL-C, LDL-C, triglyceride, adiponectin and leptin levels secreted from adipose tissue and associated with obesity were evaluated in the sera obtained from the experimental groups." (PMID 39055496, 2024). "Numerous studies have examined the relationship between leptin levels and autoimmune thyroid disease in patients with obesity." (PMID 38526760, 2024). "Thanks to research on monogenic forms of obesity, derangements in the central nervous system (CNS) pathways have been recognized, especially regarding changes in leptin (LEP) and its receptor (LEPR)." (PMID 38654832, 2024). "An important experiment left out of the current paper is what the methylation state of the leptin promoter is in obesity." (PMID 39872508, 2024). "Previous studies demonstrated that GPR10 KO mice exhibited moderate obesity when fed STD as a result of higher adiposity accompanied by elevated plasma leptin levels." (PMID 39440369, 2024). "Contrary to the findings of the present study, most research shows a positive correlation between leptin concentration and BMI, suggesting an intrinsic link with obesity, where adipokine levels generally decrease." (PMID 38737668, 2024).